KRCC1 (lysine rich coiled-coil 1)
Description:
Regulates CHEK1-mediated cell cycle checkpoint. Facilitates efficient recombination and homologous recombination repair. Required for proper S-phase progression and mitotic entry.
Synonyms: CHBP2; FLJ22333; HLY
Tractability: No criterion of Open Targets' tractability assessment is met for any kind of drug.
Gene: Protein-coding gene on chromosome 2 (88,027,203 to 88,064,252, reverse strand). Ensembl gene ENSG00000172086.
Subcellular location: Nucleus
Subcellular location (Human Protein Atlas): Cytosol; Nucleoli
Gene Ontology:
Molecular function: protein binding
Cellular component: nucleus
Genetic constraint (gnomAD): Loss-of-function variants: 8 observed, 11.5 expected, observed/expected ratio (o/e) 0.7, 90% interval 0.41 to 1.25. The upper end of that interval is the gene's LOEUF score, 1.25, which puts it in group 5 of 6, group 1 being the genes least tolerant of losing a copy. Missense variants: 277 observed, 313.15 expected, observed/expected ratio (o/e) 0.88, 90% interval 0.8 to 0.98. Synonymous variants: 102 observed, 107.63 expected, observed/expected ratio (o/e) 0.95, 90% interval 0.81 to 1.12.
Homologues: Orthologues: chimpanzee KRCC1 (98% identical), macaque KRCC1 (96% identical), rabbit KRCC1 (76% identical), pig KRCC1 (75% identical), mouse Krcc1 (74% identical), rat Krcc1 (73% identical), guinea pig Krcc1 (28% identical), Drosophila melanogaster dbf (6% identical), Drosophila melanogaster CG1231 (2% identical), zebrafish zgc:171482 (0% identical). Paralogues in human: ZMAT1 (56% identical), ZNF385B (8% identical), ZNF385C (8% identical), ZNF385D (8% identical), ZNF385A (7% identical), ZMAT2 (4% identical), ZMAT3 (2% identical), ZNF346 (2% identical), ZMAT4 (1% identical).
Diseases named in the same sentence as KRCC1 in open-access papers:
KRCC1 is named in the same sentence as 6 diseases in open-access papers, as found by Europe PMC text mining. Sharing a sentence is not in itself a finding about the gene and the disease. The quoted sentences say what the papers report.
osteosarcoma (1 paper, 2022). A usually aggressive malignant bone-forming mesenchymal neoplasm, predominantly affecting adolescents and young adults. "Silencing KRCC1 in the OV90 ovarian cancer cells and in the U2OS osteosarcoma cells significantly increased RPA2 foci formation by ∼6- and 8-fold, respectively, compared to the control cells." (PMID 36243983, 2022).
ovarian carcinoma (1 paper, 2022). A malignant neoplasm originating from the surface ovarian epithelium. "The lysine-rich coiled-coil 1 (KRCC1) protein is overexpressed in multiple malignancies, including ovarian cancer, and overexpression correlates with poor overall survival." (PMID 36243983, 2022). "We recently introduced the lysine-rich coiled-coil 1 (KRCC1), a protein with unknown biology, as a chromatin enriched nuclear protein that is frequently overexpressed in ovarian cancer and in other malignancies." (PMID 36243983, 2022).
cancer (1 paper, 2022). A tumor composed of atypical neoplastic, often pleomorphic cells that invade other tissues. "Despite a potential role in cancer progression, the biology of KRCC1 remains elusive." (PMID 36243983, 2022).
retinopathy (1 paper, 2014). "We obtained retinal tissue samples from four retinopathy affected SVs and two control dogs and used them to quantitate transcript levels of the four retinal candidate genes, MERTK, NPHP1, ANAPC1 and KRCC1 in the critical region." (PMID 25517981, 2014).
tumor (1 paper, 2025). "KRCC1, often overexpressed in malignancies, is associated with poor prognosis and impacts tumor growth and apoptosis." (PMID 40136480, 2025). "KRCC1, often overexpressed in various malignancies, is associated with poor prognosis and plays a role in promoting tumor growth and inhibiting apoptosis." (PMID 40136480, 2025).
KRCC1 also shares sentences with these, for which no sentence is quoted: infection (1 paper).